IL6 (interleukin 6)
Diseases named in the same sentence as IL6 in open-access papers (continued):
Sharing a sentence is not in itself a finding about the gene and the disease.
Sepsis (continued). "Research had found that the average level of IL-6 in patients with severe sepsis was significantly higher than that in healthy individuals (<10 pg./mL), which is tens or even hundreds of times higher than that of normal individuals." (PMID 38076268, 2023). "Among critically ill patients, those with sepsis present with pronounced increases in IL-6 production, compared to other critically ill patients with alternate diagnoses of similar severity." (PMID 36835345, 2023). "Among them, TNF-α is an important promoter of sepsis and sepsis associated ALI, inducing the production of pro-inflammatory factors such as IL-6 and IL-8 and is an important systemic reactive mediator." (PMID 38076268, 2023). "In a TLR4-induced sepsis animal model, treatment with S. thermophiles alleviates intestinal injury and decreases the serum levels of inflammatory cytokines (IL-6 and TNF-α)." (PMID 36838243, 2023). "Six studies reported detection outcomes of IL-6 in the detection of sepsis, the pooled sensitivity was 0.81 (95% CI: 0.73, 0.87; I2 = 68.8%, p = 0.007) and the pooled specificity was 0.77 (95% CI: 0.72, 0.81; I2 = 87.5%, p < 0.001), respectively." (PMID 38027268, 2023). "This study seeks to analyze IL-6 behavior in suspected early-onset sepsis (EOS) cases among term newborns, comparing it to that of CRP and evaluating IL-6’s diagnostic utility." (PMID 38255366, 2023). "Interleukin (IL)-6 is a key inflammation regulator of sepsis in NEC, and the C–C Motif Chemokine Ligand 2 (CCL2) is induced from the bone marrow to migrate white blood cells." (PMID 37217485, 2023). "IL-1Ra and IL-6 increased significantly 2 days before the diagnosis of sepsis, and both emerged superior at predicting sepsis when compared to clCAM-1 and CRP one or more days before clinical diagnosis." (PMID 36769133, 2023). "These macrophages are responsible for reducing cytokine levels, including IFNγ, TNF, IL-6, and IL-10, in patients with sepsis." (PMID 38193079, 2023). "Among several soluble cytokines, IL-6 has been reported to be a major prognostic marker of sepsis severity." (PMID 36917195, 2023). "IL-6 release can be explained by brain damage, but the additional role of sepsis during ICU treatment in certain patients cannot be excluded." (PMID 37047753, 2023). "Serum levels of IL-1β and IL-6 also significantly decreased with the use of curcumin in the treatment of sepsis, while IL-10 showed increased plasma levels." (PMID 36756300, 2023). "The potential of TNF-α, IL-1β, and IL-6 as biomarkers for patients with sepsis has been proposed, and the combined test of the three has an excellent predictive value in individuals with sepsis-induced cardiomyopathy." (PMID 37650558, 2023). "Serum cytokine IL-6 has been investigated as a predictor of early detection of postoperative sepsis." (PMID 38098074, 2023). "Some authors support that pro-inflammatory immune response in sepsis, with particularly high levels of expression of IL-6 and tumor necrosis factor (TNF), impaired acquired immunity (lymphopenia) and induced an uncontrolled innate response." (PMID 37935890, 2023). "Compared to the sepsis and vehicle groups, the Ticagrelor-pretreated group had significantly decreased lung tissue levels of pro-inflammatory cytokines (IL-6, IL1B, and TNF-α)." (PMID 37675176, 2023). "The JAK2/STAT3 signaling pathway mediates IL-6 during sepsis and delivers it to particular effector cells, which are ultimately destroyed." (PMID 37650558, 2023). "On the other hand, injection of LPS in mice induces a strong, short-term increase of plasma proinflammatory cytokines (e.g., TNF-α, IL-1β and IL-6), in comparison to the lower and progressive cytokine increase in human sepsis [,48]." (PMID 37456011, 2023). "Upregulated inflammatory cytokines (such as tumor necrosis factor (TNF)-α, interleukin (IL)-1β, IL-6, IL-8, and IL-18) are the key mediators of the pathophysiology of sepsis-induced ALI and biomarkers for predicting clinical outcomes." (PMID 36982713, 2023).
Sepsis (continued). "In vivo, linifanib effectively reduced overexpressed IL-6, a marker of sepsis severity, in the lungs of SIRS mice." (PMID 36765040, 2023). "IL-8 showed the most optimal properties in the diagnosis of early-onset sepsis in neonates as compared to IL-6, IL-8, IL-10." (PMID 38027268, 2023). "Herein, LFDsare constructed using 150–310 nm sized selenium nanoparticles(SeNPs) and are compared to commercial 40 nm gold nanoparticles (AuNPs)for the detection of the sepsis biomarker interleukin-6 (IL-6)." (PMID 36910974, 2023). "Fittingly, we have recently reported that, in a mouse model of sepsis, ICOS-deficient mice display a striking increase in blood IL-6 levels, which are substantially decreased by ICOS-Fc treatment." (PMID 36769276, 2023). "The study also documented the substantial interindividual variability in the induction of IL-6 during sepsis since it depends on the type of infection, type of bacteria, and origin of the organ involved." (PMID 38068931, 2023). "Once sepsis initiates, interleukin (IL)‐6 is rapidly released and reaches the peak level within a considerable short amount of time; the severity of which corresponds to that of infection." (PMID 37525933, 2023). "The study looked at the role of P2Y12 in controlling sepsis-induced increases in plasma cytokine levels (tumor necrosis factor-, interleukin-6, and macrophage inflammatory protein-1β)." (PMID 37675176, 2023). "In sepsis-induced kidney injury, many pro-inflammatory cytokines are released, mainly IL-1β, IL-6, and TNF-α." (PMID 36737765, 2023). "Uncoupling of IL-6 signaling and Microtubule-associated protein 1 light chain 3 (LC3)-associated phagocytosis was reported to cause immunoparalysis during sepsis." (PMID 37388447, 2023). "Overall, these data suggest that a mRCT of IL-6 inhibition in sepsis, ideally as part of a predictive enrichment approach, should at least be considered." (PMID 38057824, 2023). "The unfavorable outcome can indeed be predicted by laboratory alterations such as elevated levels of inflammatory markers such as procalcitonin, interleukin (IL)-6, and reduction in the number of leukocytes, which are also sepsis markers." (PMID 38073889, 2023). "A recent analysis of suspected LOS in preterm infants below 32 weeks of gestational age showed that serum IL-6 and PCT levels were associated with sepsis severity and mortality risk." (PMID 36980160, 2023). "IL-6/STAT3 signaling pathway plays a critical role in sepsis, modulating the inflammatory response and coagulation." (PMID 38094883, 2023). "Patients with delirium after sepsis and other conditions showed higher IL-6 and IL-8 levels than cognitively healthy patients, indicating that cytokine-induced toxicity in the brain can worsen cognitive function in septic patients." (PMID 37009158, 2023). "For example, blocking S100A9 with the inhibitor ABR-238901 greatly attenuates the CLP-induced infiltration of neutrophils, formation of edema, and expression of Mac-1, CXCL1, CXCL2 and IL-6 in the plasma or lung and improves sepsis-induced lung injury." (PMID 36768433, 2023). "We found that p-AKT was decreased while PTEN, a negative regulator of p-AKT, was increased in cells treated with TGN, LPS or IL-6, suggesting that the damage to EC function resulting from sepsis was likely mediated by the AKT pathway." (PMID 37205094, 2023). "Another recent study, which quantified IL-6 levels in patients with septic shock, showed that increasing or decreasing levels of IL-6 were far superior predictor of sepsis mortality than absolute levels of IL-6115." (PMID 38040923, 2023). "During sepsis, Kupffer cells, macrophages, and other immune cells are activated, producing numerous inflammatory mediators, including interferons, interleukin-6, interleukin-1β, interleukin-8, and tumor necrosis factor." (PMID 37575984, 2023). "It is also plausible that the beneficial effect of IL-6 blockade in sepsis is actually mediated by reductions in hsCRP." (PMID 36716318, 2023).
Sepsis (continued). "Among the sepsis biomarkers, IL-6 had the highest AUC (0.778), followed by PCT (0.744), presepsin (0.685), and CRP 0.528." (PMID 37324133, 2023). "As far as other biomarkers were concerned, they presented a positive correlation between YKL-40 and IL-6 levels in the acute phase of sepsis." (PMID 37238320, 2023). "Levels of cytokines (such as interleukin-8 [IL-8], tumor necrosis factor -α [TNF-α], IL-10, and IL-6) and endotoxins are often elevated in patients with sepsis." (PMID 36650427, 2023). "We previously showed that IL‐1β serum levels and muscular Il6 expression were reduced in septic Nlrp3 KO mice, and that these mice are protected from muscle atrophy in sepsis." (PMID 37209006, 2023). "In the case of late-onset sepsis, the decision tree incorporating inflammatory markers as PCR, PCT and IL-6 reached a diagnostic accuracy of nearly 88%." (PMID 36980160, 2023). "In this study, SJS can improve the 7-day survival rate of sepsis mice, inhibit the release of inflammatory cytokines IL-1β, IL-6, TNF-α, and increase the production of IL-10 in the early stage." (PMID 37062835, 2023). "IL-6 is an essential cytokine during the acute-phase reaction in response to inflammation and sepsis." (PMID 37366985, 2023). "The inflammatory markers IL-6, IL-10, and TNF-α are all strongly linked to the onset of sepsis, and as one of the most important inflammatory cytokines, TNF-α stimulates the production of IL-6 in endothelial cells." (PMID 36644442, 2023). "Interleukin-6 had a superior diagnostic value compared with PCT and even CRP in patients with ED diagnosed with sepsis." (PMID 36878489, 2023). "We observed significant changes in numerous CBC parameters and extended inflammation parameters (EIPs), in addition to significant biochemical analysis markers CRP and IL-6 in sepsis cohorts." (PMID 37510189, 2023). "Interleukin-6 (IL-6) is another important cytokine involved in the innate immune response in sepsis." (PMID 38057824, 2023). "These responses demonstrate a positive biological signal of splanchnic denervation when compared with our previous findings that plasma IL-6 levels temporally declined from 24 to 32-h of sepsis in sheep with established hypotensive sepsis." (PMID 37535121, 2023). "In preclinical studies, IL-6 production and concomitant TNF-suppression have also been linked to the sepsis-typical co-stimulation of endosomal and cell surface toll-like receptors." (PMID 37869001, 2023). "Previous reports indicated that the LPS-induced release of HMGB1 was associated with sepsis and that HMGB1 is an inflammatory mediator that can increase the levels of TNF-α, IL-6 and IL-1β." (PMID 38026444, 2023). "The progression of sepsis is significantly influenced by the involvement of crucial cytokines such as IL-1β, IL-18, IL-6, IL-12, IL-17, and others." (PMID 38035100, 2023). "Because of numerous studies showing the relevance of Interleukin-6 (IL-6) as an early laboratory parameter in cases of sepsis in the newborn period, IL-6 was established as a new laboratory marker." (PMID 38255366, 2023). "Numerous studies have demonstrated that interleukin (IL)-6 has good performance in sepsis diagnosis and prognosis, but its role in the development of sepsis remains controversial." (PMID 38029224, 2023). "It is a relatively novel inflammatory biomarker but a highly specific biomarker for the diagnosis of sepsis compared with interleukin-6 and PCT." (PMID 35743990, 2022). "In fact, among the cytokines whose levels are increased during sepsis, IL-6 is the one that shows a better correlation with the mortality rate." (PMID 35163089, 2022). "Compared with those in the sepsis group, the levels of IL-6, IL-1β and TNF-α were increased (P < 0.05), the MDA content was increased, while the SOD and CAT activities were decreased in the sepsis + BAY 87–2243 group (P < 0.05)." (PMID 35576220, 2022). "Proinflammatory immune biomarkers such as IL‐6, IL‐8, and IL‐10 highlight the patient status at the beginning of sepsis." (PMID 36176597, 2022).
Sepsis (continued). "Activation of this axis promotes increased expression/secretion of pro-inflammatory cytokines such as TNF-α, IL-6, IL-1β and IL-17, which in turn contribute to the cytokine storm and multiple organ failure (MOF) associated with sepsis." (PMID 36119089, 2022). "Oxytocin also impedes the endotoxin-induced increases in cortisol, TNF-α, and IL-6 in a rodent model of sepsis." (PMID 35572539, 2022). "PCT has the advantage of maintaining high serum concentrations when compared to other sepsis markers such as tumour necrosis factor-alpha (TNF) and interleukin (IL)-6, making it more useful in the identification of sepsis." (PMID 35449688, 2022). "This indicated that more than half of the G- sepsis patients had their IL-6 exceeding 270 pg/ml, while the remaining 30.8% patients had IL-6 levels exceeding 1,000 pg/ml." (PMID 36544765, 2022). "Various biomarkers, such as levels of C-reactive protein (CRP), procalcitonin (PCT), or interleukin-6 (IL-6), have been implemented in the past to diagnose suspect sepsis." (PMID 35615626, 2022). "IL-1β and IL-6 are well-known pro-inflammatory cytokines and the role of IL-1β and IL-6 in sepsis has been well documented previously." (PMID 36422559, 2022). "Giving that changes in inflammatory factors, including TNF‐α, IL‐1β, IL‐6, IL‐10, and iNOS, are a major characteristic of the sepsis model, we measured the inflammatory cytokines after LPS treatment." (PMID 35474613, 2022). "IL-6 alone, in combination with other molecules or with neutrophil-to-lymphocyte ratio can be a marker of mortality in sepsis patients." (PMID 36189302, 2022). "Correction of hypothermia during sepsis has been reported to have a positive prognostic impact by inhibiting IL-6 release." (PMID 35126812, 2022). "Circulating cardiac depressant factors such as tumor necrosis factor α (TNF-α), interleukin (IL)-6, IL-1β, NO, bacterial RNA and DNA, and lysozyme C have also been described in sepsis." (PMID 35706715, 2022). "A correlation between the CSF NT-proCNP and CSF IL-6 levels was found, suggesting a link between neuro- and systemic inflammation in sepsis." (PMID 35327328, 2022). "Substantial IL-1β, IL-6, TNF-α, and cell fragments cause renal tubular epithelial cell damage in sepsis-induced AKI." (PMID 35165294, 2022). "We found LPS-related sepsis visibly upregulated the mRNA expression of IL-6, TNF-α, pyrocytosis-related factors (such as caspase-1), hypoxia-inducible factors (such as HIF1-α), and chemokines." (PMID 35156512, 2022). "In these experiments, an improvement in mortality from sepsis by administering IL-6 antibodies has been reported." (PMID 36005726, 2022). "The results indicated that the compounds played anti-sepsis effect through inhibiting the release of NO, IL-1β, IL-6, and TNF-α mediated by LPS and regulating the LPS-TLR4/MD-2-NF-κB pathway by hydrophobic binding to the key protein MD-2." (PMID 36160407, 2022). "Compared to sepsis and vehicle groups, Montelukast pre-treatment groups had significantly reduced lung tissue levels of pro-inflammatory cytokines (IL-1B, IL-6, and IL-17)." (PMID 35928365, 2022). "The levels of IL-1, TNF-, and IL-6 in the serum of rats in the sepsis group were significantly higher, and there was more myocardial tissue edema and myocardial fiber breakage." (PMID 35982998, 2022). "IL-6 and IL-10 are comparably effective in discriminating G+/G- sepsis in pediatric intensive care unit (PICU) patients." (PMID 36544765, 2022). "S1P lyase inhibition increases S1P, reduces cytokine production including TNF-α and IL-6 and protects against sepsis via the S1P-S1PR3 axis." (PMID 35094654, 2022). "Previous studies comparing models of sepsis induced by LPS injection with CLP-induced sepsis demonstrate that the inflammatory mediators such as IL-6, TNF-α, KC, and MIP-2 show different time profiles." (PMID 35648977, 2022).
Sepsis (continued). "IL-6 serves as a major mediator during the early phase of the acute response to inflammation in sepsis, and its clinical importance has been assessed in several studies on patients with various septic conditions." (PMID 35955767, 2022). "Following sepsis, we tested candidate MK growth factors and observed decreased splenic expression of Tpo, Csf2, and Ccl5, while Il1b was unchanged and Il3 and Il6 were significantly increased." (PMID 35192546, 2022). "Herein, we found that AE was able to alleviate associated changes in spleen index and suppress LPS-induced TNF-α, and IL-6 production, suggesting that it plays an important protective role as an anti-inflammatory agent in our murine sepsis model." (PMID 35978995, 2022). "IL-6 belongs to the cytokine network that regulates the acute phase of response to inflammation in sepsis." (PMID 35167625, 2022). "Several biomarkers, such as procalcitonin, C-reactive protein, interleukin (IL)-6, and other inflammatory factors, have been proposed for sepsis detection." (PMID 35991069, 2022). "Our data disagree with those of previous studies of LPS-induced sepsis that found decreased plasma concentrations of IL-6, TNF-α, and MIP-2 in mice treated with riboflavin 6 h after LPS injection (14-, 16)." (PMID 35648977, 2022). "We found that TNF-α, IL-6, and IL-1β were significantly increased in the sepsis group, offset by 3PO and Gsdmd gene deletion." (PMID 36589684, 2022). "We found that the serum concentration of IL-6 and TNF-α, two pro-inflammatory cytokines regularly associated with sepsis, differed between both groups of mice only after the re-emergence of bacteria from the spleen." (PMID 35720383, 2022). "In ARDS, lung injury is responsible for the release of pro-inflammatory mediators similar to sepsis (IL-6, PAI-1, soluble TNF receptors)." (PMID 37675005, 2022). "The results in this also showed that EA at ST36 inhibited the production of TNF-α, IL-1β, and IL-6 and increased IL-10 production in septic mice, suggesting its therapeutic effect on sepsis." (PMID 35722155, 2022). "Upon binding with its cognate receptor, IL-6 receptor (IL-6R), and subsequent activation of the downstream Akt pathway, IL-6 can induce vascular endothelial breakdown and aggravate organ injury (e.g., the lungs) during sepsis." (PMID 35337084, 2022). "The overexpression of many proinflammatory cytokines, such as TNF-α, IL-1β, and IL-6, is closely related to severe sepsis." (PMID 35370629, 2022). "Our research showed significantly higher lung tissue levels of pro-inflammatory cytokines (IL1B, IL-6, and IL-17) in sepsis and vehicles groups compared with the sham group, corresponding to other findings." (PMID 35928365, 2022). "IL-6 can stimulate synthesis of acute phase proteins and modulate activation of immune cells during sepsis." (PMID 35337084, 2022). "IL-6 is a proinflammatory cytokine, and its production is triggered within minutes of numerous systemic insults, such as surgery, trauma, and sepsis, as part of the systemic inflammatory response syndrome (SIRS), which also occurs during AKI." (PMID 35491874, 2022). "Cardiac-specific overexpression of IL-6 has been reported to deteriorate systolic dysfunction, inflammation, and apoptosis in mice after burn plus sepsis, whereas these changes were reportedly attenuated in IL-6 knockout mice." (PMID 39802494, 2022). "Our previous study indicated that CRRT significantly decreases serum levels of TNF-α and IL-6 in sepsis." (PMID 36263056, 2022). "Among these factors, TNF-α plays a key role in the pathogenesis of sepsis, and IL-1β and IL-6 participate in the initiation of the sepsis cascade and reflect the degree of inflammation." (PMID 35576220, 2022). "The blood glucose level of patients with sepsis was positively correlated with the levels of IL-6, TNF-α, and IL-1β." (PMID 35664433, 2022).